CLEC12B (C-type lectin domain family 12 member B)
Description:
Inhibitory receptor postulated to negatively regulate immune and non-immune functions. Upon phosphorylation, recruits SH2 domain-containing PTPN6 and PTPN11 phosphatases to its ITIM motif and antagonizes activation signals. Although it inhibits KLRK1/NKG2D-mediated signaling, it does not bind known ligands of KLRK1/NKG2D and therefore is not its inhibitory counterpart. May limit activation of myeloid cell subsets in response to infection or tissue inflammation. May protect target cells against natural killer cell-mediated lysis. May negatively regulate cell cycle and differentiation of melanocytes via inactivation of STAT3.
Synonyms: UNQ5782
Tractability: Antibody: UniProt places it where antibodies can reach, with high confidence; UniProt predicts a signal peptide or a membrane-spanning region; its Gene Ontology location is reachable by antibodies, with medium confidence.
Gene: Protein-coding gene on chromosome 12 (10,010,627 to 10,018,796, forward strand). Ensembl gene ENSG00000256660.
Subcellular location: Cell membrane
Gene Ontology:
Molecular function: protein phosphatase binding; signaling receptor inhibitor activity; signaling receptor regulator activity
Biological process: melanocyte proliferation; natural killer cell inhibitory signaling pathway; negative regulation of natural killer cell mediated cytotoxicity; negative regulation of receptor signaling pathway via STAT; negative regulation of signaling receptor activity
Cellular component: external side of plasma membrane; plasma membrane; protein-containing complex
Genetic constraint (gnomAD): Loss-of-function variants: 17 observed, 28.51 expected, observed/expected ratio (o/e) 0.6, 90% interval 0.41 to 0.89. The upper end of that interval is the gene's LOEUF score, 0.89, which puts it in group 3 of 6, group 1 being the genes least tolerant of losing a copy. Missense variants: 227 observed, 244.29 expected, observed/expected ratio (o/e) 0.93, 90% interval 0.83 to 1.04. Synonymous variants: 88 observed, 86.58 expected, observed/expected ratio (o/e) 1.02, 90% interval 0.86 to 1.21.
Homologues: Orthologues: chimpanzee CLEC12B (98% identical), macaque CLEC12B (96% identical), dog CLEC12B (82% identical), rabbit CLEC12B (79% identical), pig CLEC12B (78% identical), mouse Clec12b (71% identical), rat Clec12b (69% identical), Drosophila melanogaster rgn (18% identical), zebrafish si:ch211-193e13.5 (18% identical), zebrafish si:dkey-26c10.5 (16% identical), zebrafish si:ch211-170d8.8 (15% identical), Caenorhabditis elegans clec-146 (13% identical), and 1 more. Paralogues in human: CLEC1A (33% identical), CLEC12A (27% identical), OLR1 (25% identical), CLEC9A (24% identical), CLEC1B (24% identical), CLEC7A (24% identical), KLRC1 (22% identical), KLRC2 (19% identical), KLRD1 (19% identical), KLRG1 (19% identical), KLRK1 (19% identical), KLRF1 (18% identical), and 11 more.
Diseases named in the same sentence as CLEC12B in open-access papers:
CLEC12B is named in the same sentence as 5 diseases in open-access papers, as found by Europe PMC text mining. Sharing a sentence is not in itself a finding about the gene and the disease. The quoted sentences say what the papers report.
myeloma (1 paper, 2023). "We selected genes (ARHGAP26, MYH10, PMP2, RFX8, BAMBI, CLEC12b) with significant changes in methylation level to validate their expression using qRT-PCR in U266 myeloma cells." (PMID 38201971, 2023).
cancer (2 papers, 2022 to 2023). A tumor composed of atypical neoplastic, often pleomorphic cells that invade other tissues. "Among them, CISD1 was also found to be closely linked to CLEC12B, CLEC2B and CSTA in a variety of cancers, with CLEC2B being involved in the largest number of cancer types." (PMID 36030279, 2022). "After investigating the pan-cancer section of ENCORI, an online tool, CISD1 was discovered to be highly linked to CLEC2B, CLEC12B and CSTA in a variety of cancer types." (PMID 36030279, 2022). "The most important observations are the hypomethylation of the CLEC12B and BAMBI genes, which are responsible for inhibiting the proliferation of cancer cells." (PMID 38201971, 2023).
bacterial infections (1 paper, 2024). "In this study, highly consistent profiles of CLEC12B were also observed, highlighting the involvement of NCCs in the defense of the tilapia brain against bacterial infections." (PMID 39011038, 2024).
CLEC12B also shares sentences with these, for which no sentence is quoted: COVID-19 (1 paper); lung carcinoma (1).